HTR1B (5-hydroxytryptamine receptor 1B)
Diseases named in the same sentence as HTR1B in open-access papers (continued):
Sharing a sentence is not in itself a finding about the gene and the disease.
schizophrenia (continued). "Other SNPs had not been found to be associated with schizophrenia, but still provide references for HTR1B gene polymorphisms in the northern Han Chinese population." (PMID 30231895, 2018). "Although three known functional sites (rs11568817, rs130058, rs13212041) were found in our study, we discovered no direct associations between HTR1B and schizophrenia by haplotype." (PMID 30231895, 2018). "Therefore, we proposed that ALKBH5 and HTR1B may serve as potential blood biomarkers for diagnosing and individualizing pharmacotherapy for patients with schizophrenia, highlighting a novel avenue for therapeutic targeting." (PMID 37990254, 2023). "Since we have found a significant association of the HTR1B rs13212041 polymorphism with scores on the BARS scale, which is used for rating akathisia, we evaluated akathisia in haloperidol-treated patients with schizophrenia using the SAS and ESRS scales as well." (PMID 32231051, 2020). "HTR1B has been suggested to be associated with multiple emotional and psychiatric problems, including attention deficit hyperactivity disorder (ADHD), antisocial behavior, aggressive behavior, bipolar disorder, anxiety/depression, schizophrenia and substance abuse." (PMID 30231895, 2018). "HTR1B, ALKBH5, and Arc exhibited higher levels in individuals with first-episode schizophrenia compared to the controls and showed a strong positive correlation with ERVWE1." (PMID 37990254, 2023). "Herein, higher levels of HTR1B, Arc, and ALKBH5 were detected in schizophrenia patients compared with the healthy controls and had a positive correlation with ERVWE1." (PMID 37990254, 2023). "Taking together, higher levels of HTR1B and ALKBH5 in the blood of schizophrenia patients positively correlated with ERVWE1, and ALKBH5 was a novel schizophrenia risk gene." (PMID 37990254, 2023). "A set of 29 SNPs of genes of serotonin receptors HTR1A, HTR1B, HTR2A, HTR2C, HTR3A, HTR3B, and HTR6 was studied in a population of 449 Caucasians (226 females and 223 males) with verified clinical diagnosis of schizophrenia (according to ICD-10: F20)." (PMID 32390801, 2020). "Subsequent analysis revealed several positive correlations between ERVWE1 and HTR1B (p = 0.01, r = 0.65), Arc (p = 0.03, r = 0.57), and ALKBH5 (p < 0.01, r = 0.78) in the mRNA levels of schizophrenia patients, as determined by Spearman's correlation." (PMID 37990254, 2023). "Strikingly, plasma HTR1B concentration also correlated significantly with plasma 5-HT, Arc, and ALKBH5 concentration in schizophrenia patients (r = − 0.6 in 5-HT, r = 0.6 in Arc, r = 0.7 in ALKBH5), indicating that HTR1B was associated with m6A modification in schizophrenia." (PMID 37990254, 2023). "We observed higher levels of HTR1B, Arc, and ALKBH5 in individuals with schizophrenia." (PMID 37990254, 2023). "Importantly, HTR1B, Arc, and ALKBH5 had a strong positive correlation with ERVWE1 in schizophrenia patients." (PMID 37990254, 2023). "ERVWE1 impaired 5-HT neuronal plasticity in ALKBH5-m6A dependent mechanism by the HTR1B-ERK-ELK1-Arc pathway, which may be an important contributor to aberrant synaptic plasticity in schizophrenia." (PMID 37990254, 2023). "Mechanistically, ERVWE1 upregulated HTR1B through ALKBH5-mediated m6A-dependent epigenetic modifications, contributing to the impairment of 5-HT neuronal plasticity by activating the ERK-ELK1-Arc signal pathway in schizophrenia." (PMID 37990254, 2023). "Interestingly, HTR1B also showed positive correlations with ALKBH5 and Arc in schizophrenia." (PMID 37990254, 2023). "In this article, we reported that ERVWE1 amplified the expression of HTR1B, p-ERK1/2, p-ELK1, and Arc in SH-SY5Y cells and 5-HT neurons, indicating that ERVWE1 could upregulate Arc expression through the ERK cascade, thus potentially participating in the development of schizophrenia." (PMID 37990254, 2023).
Obesity (5 papers, 2012 to 2025). Accumulation of substantial excess body fat. "A previous study has shown that expression of HTR1B increased significantly when mice were given a drug to treat obesity." (PMID 32331314, 2020).
pulmonary hypertension (5 papers, 2017 to 2025). Increased pressure within the pulmonary circulation due to lung or heart disorder. "The expression of receptors associated with pulmonary hypertension and RV remodeling such as receptor (HTR1B), BMPR2 and endoglin were not affected by MA." (PMID 33789156, 2021).
alcoholism (4 papers, 2011 to 2025). "Thus, HTR1B polymorphisms were reported to be associated significantly with alcoholism with antisocial behaviors, whole alcoholism, substance dependence and heroin addiction, although there were also several inconsistent reports." (PMID 21886584, 2011). "These inconsistencies among alcoholism studies may indicate that status of comorbidity with other substance abuse could influence the results because HTR1B was shown to be associated with substance abuse and heroin addiction." (PMID 21886584, 2011).
autism (3 papers, 2016 to 2022). Persistent deficits in social interaction and communication and interaction as well as a markedly restricted repertoire of activity and interest as well as repetitive patterns of behavior. "A case–control study in 252 individuals with autism spectrum disorder suggested a role for HTR1B in the predisposition to autism, since such individuals more often had polymorphic HTR1B variants that were known to have a lower expression." (PMID 29904178, 2018). "Apart from these four known genes, the genes HTR1E (5-hydroxytryptamine receptor 1E, MIM*182132) and HTR1B (5-hydroxytryptamine receptor 1B MIM*182131), which did not pass our strict HI score, may also play a role in autism-like behaviour." (PMID 29904178, 2018).
bipolar disorder (3 papers, 2024 to 2025). A disorder of the brain that causes unusual shifts in mood, energy, activity levels and the ability to carry out day-to-day tasks. "While HTR1A, HTR2A, and HTR7 are known targets of lurasidone, MAOB, HTR3A, SLC18A2, and HTR1B were identified for the first time as targets of lurasidone potentially involved in its associated induction of acute manic episodes in people with bipolar depression." (PMID 40202273, 2025). "HTR2A and HTR1B exhibited the highest binding affinities among the seven target proteins, suggesting that these proteins may be the ones largely responsible for lurasidone‐induced treatment‐emergent mania in people with bipolar depression." (PMID 40202273, 2025). "Our bioinformatics and computational analyses demonstrated that lurasidone may regulate the serotonergic synapse signaling pathway by targeting proteins such as MAOB, HTR1A, HTR2A, HTR3A, SLC18A2, HTR1B, and HTR7 to induce treatment‐emergent mania in people with bipolar depression." (PMID 40202273, 2025). "This study revealed that lurasidone may regulate the serotonergic synapse signaling pathway by interacting with the identified core targets MAOB, HTR1A, HTR2A, HTR3A, SLC18A2, HTR1B, and HTR7 to induce treatment‐emergent mania in people with bipolar depression." (PMID 40202273, 2025).
breast carcinoma (3 papers, 2016 to 2023). "In luminal-A breast cancer subtype, the results revealed that the increased levels of HTR1B/1D/1E/1F/2A/2C/3A/4/6 were significantly related to better RFS (p< 0.05)." (PMID 37795441, 2023). "One possible example is Htr1b which has been identified in previous breast cancer gene expression studies, but later shown to be a consequence of variable expression from the stromal population within a tumor sample." (PMID 27711132, 2016). "It has also been shown that HTR1B/1D agonists could induce breast cancer cell death." (PMID 37795441, 2023). "The expression levels of HTR1A, HTR1B, HTR2A, HTR2B, HTR2C, HTR4, and HTR7 were significantly downregulated in highly malignant breast cancer types." (PMID 37795441, 2023). "The HTR1B gene has been suggested to be involved in breast cancer progression and the HMGN3 gene has been published to be upregulated in breast cancer cell lines." (PMID 29262523, 2017). "However, when compared to normal breast tissue, HTR1A, HTR1B, HTR2A, HTR2B, HTR2C, HTR4, and HTR7 were suppressed in high malignancy breast cancer types, whereas they were highly expressed in low malignant breast cancer." (PMID 37795441, 2023). "In addition, the mRNA levels of HTR1B were not significantly changed in all breast cancer subtypes compared with normal breast tissue, and the mRNA for HTR1A/3B/5A were barely expressed." (PMID 37795441, 2023).
colorectal cancer (3 papers, 2018 to 2024). A primary or metastatic malignant neoplasm that affects the colon or rectum. "Two serotonin genes, Htr7 and Htr1b, were in common between the chemically-induced colorectal cancer mouse model and the previous mouse model exposed to E171 only." (PMID 29950665, 2018).
mental disorder (3 papers, 2020 to 2024). A disease that has its basis in the disruption of mental process. "For example, the serotonin receptor gene HTR1B has been related to human mental disorders and associated with aggressive behavior in dogs." (PMID 38324050, 2024). "The HTR1B gene encodes the 5-hydroxytryptamine (5-HT1B) receptor, which is involved in a variety of brain activities and mental disorders." (PMID 32689951, 2020).
attention deficit-hyperactivity disorder (2 papers, 2018). A disorder characterized by a marked pattern of inattention and/or hyperactivity-impulsivity that is inconsistent with developmental level and clearly interferes with functioning in at least two settings (e.g. at home and at school). "•The relationship between attention-deficit hyperactivity disorder and HTR1B and DBH genes has not studied before." (PMID 30246098, 2018). "The present study was aimed to investigate the relationship between polymorphism of serotonin receptor 1B gene (HTR1B) and Dopamine beta-hydroxylase gene (DBH) with attention-deficit hyperactivity disorder in adults with or without substance use disorders." (PMID 30246098, 2018). "The findings indicated that genotype and allele frequency difference of HTR1B (rs130058) and DBH (rs2519152) genes are not different in the attention-deficit hyperactivity disorder group, substance use disorder group, the group with patients suffering from both disorders, and control group." (PMID 30246098, 2018).
behavior disorder (2 papers, 2020 to 2024). "This study investigated the effect of several HTR1B haplotypes on regulation of gene expression in vitro and the functional sequences in the 5′ regulatory region of HTR1B to determine their potential association with mental and behavioral disorders." (PMID 33036580, 2020). "Genome-wide association studies have shown that HTR1B polymorphisms are closely related to multiple mental and behavioral disorders; however, the functional mechanisms underlying these associations are unknown." (PMID 33036580, 2020).
COVID-19 (2 papers, 2021 to 2022). A disease caused by infection with severe acute respiratory syndrome coronavirus 2. "The primary aim of this study was to investigate the possible associations between selected SNPs of OPRM1 (rs1799971), COMT (rs4680), BDNF (rs6265), and HTR1B (rs6296) and the presence of de novo long-term post-COVID pain in previously hospitalized COVID-19 survivors." (PMID 35893072, 2022). "This exploratory study showed that four polymorphisms associated with pain experience (SNPs of OPRM1 (rs1799971), COMT (rs4680), BDNF (rs6265), and HTR1B (rs6296)), did not appear to predispose for developing post-COVID pain in previously hospitalized COVID-19 survivors." (PMID 35893072, 2022). "The current study did not reveal significant differences in the presence of OPRM1 (rs1799971), COMT (rs4680), BDNF (rs6265), and HTR1B (rs6296) SNPs between previously hospitalized COVID-19 survivors with and without post-COVID pain." (PMID 35893072, 2022).
liver cancer (2 papers, 2018 to 2024). An epithelial or non-epithelial malignant neoplasm that arises from the liver. "Research showed that 32% and 35% of liver cancer patients had HTR1B and HTR2B expression, respectively, both of which were linked to higher cell growth." (PMID 39766808, 2024). "Furthermore, we demonstrated that inhibition of HTr1B and HTr2B reduced serotonin-mediated cell steatosis since these receptors are involved in liver cancer cell proliferation and tumor development." (PMID 30409162, 2018).
methamphetamine dependence (2 papers, 2011 to 2025). A drug dependence that is a psychological dependency on the regular use of methamphetamine. "We examined a case-control genetic association study of HTR1B with methamphetamine-dependence patients in a Japanese population." (PMID 21886584, 2011). "Therefore, in order to investigate the roles of HTR1B in substance dependence, we examined a possible genetic association of HTR1B with methamphetamine dependence in a Japanese population." (PMID 21886584, 2011). "The present findings may indicate that HTR1B does not play a major role in individual susceptibility to methamphetamine dependence or development of methamphetamine-induced psychosis." (PMID 21886584, 2011). "Therefore, our negative findings may be significant and indicate that higher or lower density of the 5HT1b receptor due possession of -161A or -161T of HTR1B does not affect individual susceptibility to methamphetamine dependence and psychosis." (PMID 21886584, 2011).
osteosarcoma (2 papers, 2021 to 2025). A usually aggressive malignant bone-forming mesenchymal neoplasm, predominantly affecting adolescents and young adults. "By contrast, several genetic studies have shown a decreased 5-hydroxytryptamine receptor 1B gene (HTR1B) in the lung, renal, osteosarcoma, and non-Hodgkin’s lymphoma, suggesting that serotonin may behave as a tumor suppressor when it interacts with 5-HTB receptor subtypes." (PMID 33525332, 2021).
acute myeloid leukaemia (1 paper, 2024). "Serotonin receptor type 1B (HTR1B) was found to be expressed by various solid tumours, and also primary bone marrow mononuclear cells from myelodysplastic neoplasm and acute myeloid leukaemia patients, representing a potential therapeutic target." (PMID 39183370, 2024).
Ataxia (1 paper, 2024). Ataxia refers to impaired coordination of voluntary muscle movement. "Interestingly, among the 24 PC genes with restored expression, seven genes (Abr, Calb1, Htr1b, Itpr1, Kcnip1, Kcnma1, and Mtss1) were part of a group of 80 PC-type-specific downregulated genes common to the SCA1, SCA2, and SCA7 mouse models and composed an ataxia molecular signature." (PMID 38673939, 2024).
autism spectrum disorder (1 paper, 2018). A spectrum of developmental disorders that includes autism, and Asperger syndrome. "Remarkably, we observed an autism spectrum disorder in 7/13 individuals with an HTR1E and a SYNCRIP deletion, while the numbers were 3/13 for RIMS1, 3/12 for HTR1B, 3/14 for PHIP and 4/10 for ZNF929." (PMID 29904178, 2018).
chronic myelomonocytic leukaemia (1 paper, 2024). "HTR1B had been proposed as a therapeutic target in myelodysplastic syndrome (MDS), as well as in chronic myelomonocytic leukaemia (CMML)." (PMID 39183370, 2024).
essential thrombocythemia (1 paper, 2024). A chronic myeloproliferative neoplasm that involves primarily the megakaryocytic lineage. "In this study we assessed for the first time the expression levels of HTR1B mRNA in the peripheral blood mononuclear cells (PBMC) of 85 newly diagnosed MPN patients, consisting of 28 polycythemia vera, 25 essential thrombocythemia and 32 primary myelofibrosis cases." (PMID 39183370, 2024).
gestational diabetes mellitus (1 paper, 2025). "Moreover, two UTR variants (rs1063320 and rs6296) in HLA-G and HTR1B were associated with the risk of T2D in the studied population, and studies have also identified the association of HLA-G in the risk of gestational diabetes mellitus and type 1 diabetes." (PMID 39747296, 2025).
glioblastoma (1 paper, 2024). The most malignant astrocytic tumor (WHO grade IV). "The high expression of HTR1D and HTR2C was negatively related to the OS of HNSC, and almost all the HTGPCR genes, except HTR1B and HTR4, were related to the prognosis of glioblastoma." (PMID 39766808, 2024).
Hepatic steatosis (1 paper, 2022). Steatosis is a term used to denote lipid accumulation within hepatocytes. "Importantly, these results are supported by the expression of tissue-specific HTRs, such as HTR1B, HTR2A, HTR2B and HTR7, in the liver, the relationship of HTR2A with hepatic steatosis and that of HTR2B with hepatocyte proliferation." (PMID 35765850, 2022).
invasive lobular breast carcinoma (1 paper, 2023). An infiltrating lobular adenocarcinoma of the breast. "In Turashvili Breast Statistics, HTR1B was overexpressed in invasive lobular breast carcinoma with a FC of 2.181, while it was downregulated in Radvanyi Breast Statistics." (PMID 37795441, 2023).
metastatic prostate carcinoma (1 paper, 2024). A carcinoma that arises from the prostate gland and has spread to other anatomic sites. "PAAD progression involves various serotonin receptor subtypes at distinct tumor phases, with significant HTR1A and HTR1B expression observed in aggressive PAAD characterized by high Gleason scores and metastatic prostate cancer." (PMID 39766808, 2024).
mood disorder (1 paper, 2013). A cognitive disorder a disturbance in which the person's mood is hypothesized to be the main underlying feature. "Genetic variants in genes related to serotonin transmission (e.g. HTR1B,HTR3A, HTR5A, etc) were associated with mood disorder." (PMID 23326387, 2013).
myeloid neoplasm (1 paper, 2018). Proliferation of myeloid cells originating from a primitive stem cell. "Our results support a further clinical development of novel treatment strategies based on HTR1B antagonists in combination with DRs’ antagonists for myeloid neoplasms." (PMID 30224768, 2018).
pancreatic adenocarcinoma (1 paper, 2024). "Our findings revealed elevated HTR1B levels in advanced pancreatic adenocarcinoma (PAAD) but did not demonstrate a correlation between HTR1A and PAAD tumor stages." (PMID 39766808, 2024).
prostate carcinoma (1 paper, 2025). A carcinoma that arises from epithelial cells of the prostate gland. "We also reanalyzed Beltran’s clinical prostate cancer bulk RNA-Seq data on NEPC liver metastasis and found that the HTR1B was the most highly expressed HTR at the mRNA level in NEPC liver metastatic biospecimens." (PMID 39903533, 2025).
Sch (1 paper, 2023). "As a result, a positive association was noted between the carriage of the homozygous genotype TT of rs13212041 (NC_000006.12:g.77461407C>T) of the HTR1B gene with the risk of AIA in patients with Sch according to the BARS scale (p-value = 0.004)." (PMID 36980888, 2023).
thrombosis (1 paper, 2024). "We acknowledge that our study is limited by the low number of patients, especially from the non‐MPN thrombosis group and more studies are required to determine which cells overexpress HTR1B and exactly how is this related to thrombosis." (PMID 39183370, 2024). "However, at clinical data examination, it was observed that MPN patients with a recent history of major thrombosis and/or signs of impaired microcirculation exhibited significantly higher HTR1B expression levels compared to non‐thrombotic MPNs and control group." (PMID 39183370, 2024). "Moreover, thrombotic MPN patients had significantly higher HTR1B expression than patients with recent thrombosis and absence of MPN diagnostic criteria." (PMID 39183370, 2024). "When comparing the level of HTR1B expression between MPN patients with/without thrombosis, non‐MPN thrombotic patients and control group a statistically significant difference was noted (p < 0.0001, Kruskal–Wallis test)." (PMID 39183370, 2024).